LHB (luteinizing hormone subunit beta)
Diseases named in the same sentence as LHB in open-access papers (continued):
Sharing a sentence is not in itself a finding about the gene and the disease.
depression (continued). "Strategic position of LHb in regulation of the monoamines, such as serotonin and dopamine, prompted researchers to hypothesize a role of LHb in psychiatric disorders such as depression." (PMID 24339810, 2013). "Chronic activation of the dopaminergic inputs to LHb might contribute to the hyperactivation of the habenula in depression." (PMID 24339810, 2013). "Thus, decreasing LHb neuronal activity has been reported to improve behavior in a rat model of depression and also to reduce symptoms of depression in some patients." (PMID 22485164, 2012). "Overactivity of the LHb may therefore contribute to the pathogenesis of depression by inhibiting the raphe." (PMID 19064356, 2009). "Given the essential role of the LHb in regulation of depression, we next assessed whether the expression patterns of MDGA1 and Nlgn2 were changed using a mouse model of chronic stress, which is a major risk factor for depression onset." (PMID 39897557, 2025). "In fact, the LHb has been implicated in coding of negative emotions and is aberrantly hyperactive in individuals with depression." (PMID 36527355, 2023). "Thus, the LHb is a stress‐responsive structure essential for the onset and treatment of depression." (PMID 34963191, 2022). "Withdrawal-induced symptoms, such as depression, could be regulated by LHb AMPAR." (PMID 36386995, 2022). "For these reasons, the LHb may be an important therapeutic target for depression." (PMID 35784832, 2022). "Thus, the LHb is a potential target for EA intervention in depression." (PMID 33436036, 2021). "In humans, functional studies revealed its hyperactivity in individuals with major depression, and deep brain stimulation to the inactive LHb reported either full revision or alleviation of MDD." (PMID 34639188, 2021). "Thus, the LHb is thought to have a role in the progression of depression and drug abuse." (PMID 33143210, 2020). "Furthermore, animal models of depression are accompanied by synaptic potentiation onto LHb neurons in mice, which can be alleviated with antidepressants, suggesting an important role of LHb afferents in mediating depressive symptoms." (PMID 30855228, 2019). "In this view, LHb may act as a general hub for the connection between pain and depression." (PMID 30804373, 2019). "Moreover, the finding that despite the differences in the duration of treatment required, novel and conventional antidepressant therapies reverse LHb hyperexcitability highlight the importance of the LHb in developing more selective and rapid acting therapeutic strategies for depression." (PMID 30581384, 2018). "Additional LHb circuits that have been implicated in depression have not yet been evaluated." (PMID 30581384, 2018). "However, it is still unclear whether the LHb plays a role in chronic neuropathic pain-related depression by affecting the DRN." (PMID 28270756, 2017). "Given that depressive behaviors involve abnormal responses to stressors and the hyperactivity of the LHb, our results support the idea that suppressing LHb activity may represent a potentially effective approach for treating depression." (PMID 28561735, 2017). "However, several studies showed that the LHb is involved in other brain functions, such as reward, aversion, cognition, maternal behavior, sleep, and circadian rhythms, and in brain dysfunctions, such as addiction, depression, and schizophrenia." (PMID 26779042, 2015). "Similarly, neuronal inhibition of the LHb by deep brain stimulation has shown ameliorating effects in the CMS model of depression while pharmacological inhibition of the LHb mediates an antidepressant effect in an animal model of treatment resistant depression." (PMID 24339877, 2013). "Moreover, the raphe nuclei are implicated in major depression, an illness which can be precipitated or exacerbated by disruptions of circadian alignment through jet lag or shift work, and an expanding body of evidence highlights the functional importance of raphe-LHb pathways in major depression." (PMID 20547209, 2010).
depression (continued). "As a key target of pain modulation, LHb also sends outputs to the dorsal raphe nucleus (DRN) to modulate pain and depression-like behaviors." (PMID 37712096, 2023). "The results suggest that increased LHb-DRN pathway activity explains the coexistence of pain and depression." (PMID 37712096, 2023). "Taking all the evidence together, light therapy is effective for alleviating sleep disturbance with comorbid depression (SDCD), and the light-responsive LHb and SCN form a dual-core system for alleviating SDCD." (PMID 37768984, 2023). "This is in contrast with the most common finding of pre-clinical models of depression, where NMDA receptor–dependent LHb bursting are also elevated and is shown to be the critical target for anti-depressant effects of ketamine." (PMID 35972745, 2023). "Specifically, chemogenetic tools have been used to alter behavior in anxiety- and depression-related tests by manipulating the activity of VTA, NAc, mPFC, HF, LHb, and DRN." (PMID 33589739, 2022). "Considering the putative role of the LHb in targeted responses to negative prediction errors, modified GR-IR in this area could lead to distorted reward processing, a condition associated with depression." (PMID 35990727, 2022). "Striosomes, while carrying the supporting value of reward, which is distorted in major depression, produce an enriched CB1R expression via the dendron and through the LHb pathway, suggesting a critical junction for treating major depression." (PMID 33668515, 2021). "Thus, LHb hyperactivity and enhanced glutamatergic transmissions during both DD and AUD states may be the cellular and molecular mechanisms underlying LHb’s role in the connection between depression and addiction." (PMID 33143210, 2020). "Surprisingly, very few studies have focused on the contribution of the LHb–DRN pathway to stress and stress-related psychiatric disorders, including anxiety and depression." (PMID 27785462, 2016). "Surprisingly, we found that while there are clear memory impairments with chemogenetic activation of the LHb, this manipulation does not drive depression." (PMID 40799491, 2025). "Surprisingly, we found that transient activation of LHb impaired long-term memory, without affecting anxiety or depression-like behaviors." (PMID 40799491, 2025). "The LHb mediates negative emotions and is most widely studied in cases of depression mainly due to its abnormal excitation." (PMID 36756128, 2023). "Considering these results, it is not surprising that the LHb has become the focus of studies in the pathogenesis of depression." (PMID 30356828, 2018). "The clinical studies discussed in this review suggest that targeting the LHb with DBS supports its therapeutic potential, however less clear is the efficacy of pharmacological strategies acting at the level of this nucleus to treat depression." (PMID 30083090, 2018). "Although to date the LHb rather than the MHb has been discussed in the context of depression, there is accumulating evidence for an involvement for the MHb." (PMID 30250120, 2018). "In conclusion, the LHb and the DRN play important roles in the regulation of depression and pain." (PMID 28270756, 2017). "In mice, learned helplessness (an animal model for studying depression-like symptoms) results in potentiation of LHb outputs, suggesting an increase in negative neural signaling." (PMID 24734015, 2014). "In addition, a new study in rat models of depression revealed that tetanic, high-frequency DBS of the LHb suppressed synaptic activity of LHb VTA-projecting neurons and improved depressive-like behaviors." (PMID 24376408, 2013). "Understanding the relationship between the MHb and both the LHb and IPN may reveal insight into depression and mood disorders and should be a future area of study." (PMID 24478666, 2013).
depression (continued). "LHb neuronal responses to chemogenetic activation of the LH-LHb pathway or acute restraint stress were similarly muted in the Nlgn2mut/mut mice, confirming that decreased binding of MDGA1 to Nlgn2 is specifically required for conferring resistance to stress-induced depression." (PMID 39897557, 2025). "In general, LHb hyperactivity is a common finding in negative affective states including anhedonia, lack of motivation and social withdrawal, the hallmarks of reward deficits and depression 22–25." (PMID 38798343, 2024). "That study found that the activity of the DRN5-HT+-CeASOM+ circuit is decreased in the comorbid condition of pain, anxiety, and depression, and that activation of the DRN5-HT+-CeASOM+-LHb circuit could reverse the nerve injury-induced reduction in pain threshold and the depression-like behavior." (PMID 35211169, 2022). "Furthermore, we showed that increases in the LHb-DRN pathway activity were a common neurobiological mechanisms for pain and depression, which may explain the coexistence of pain and depression." (PMID 28270756, 2017). "The LHb is an epithalamic structure containing glutamatergic neurons involved in various processes such as the regulation of sleep, negative reward prediction, stress, learned helplessness, depression and behavioral inhibition." (PMID 23840355, 2013). "Although recent research has suggested that the LHb is an important circuit in depression and that constant activation may be a contributing factor to the pathology of depression, it does not take into consideration the altered activation of GABA and Glu neurons in different brain regions." (PMID 37732313, 2023). "Based on these experiments, we can speculate that the LHb interacts with the 5-HT system, modulates N-methyl-D-aspartic acid (NMDA) and aminomethyl phosphonic acid (AMPA) receptors, and has a bidirectional connection with the HPA axis to regulate the stress-related adaptive response to depression." (PMID 33436036, 2021). "Given the pivotal role of the LHb in regulation of midbrain nuclei activity and therefore in reward-related behaviors, it was suggested that modulation of this region by DBS might be an effective therapeutic tool for psychiatric disorders, including major depression, and drug addiction." (PMID 24376408, 2013). "Because this group focused on the comorbidity of pain and depression, they did not check the role of the DRN5-HT+-CeASOM+-LHb circuit in anxiety-like behaviors." (PMID 35211169, 2022).
Anxiety (42 papers, 2013 to 2025). Intense feelings of nervousness, tension, or panic often arise in response to interpersonal stresses. "Located between the dorsomedial thalamus and the third ventricle, reductions in LHb volume and neuronal density have been linked to increased anxiety-like behaviors." (PMID 40635883, 2025). "Excessive LHb activity, often triggered by stress-induced anxiety, contributes to helplessness, loss of sensation, and reduced motivation." (PMID 40635883, 2025). "Inactivation of the LHb by GABA receptor agonists attenuates the anxiolytic-like effects as seen by an increased time staying in the open arms of the EPM test, again indicating an association between the LHb and anxiety." (PMID 35145415, 2022). "In the present study, we investigated the involvement of the LHb in the mechanisms underlying allodynia and anxiety induced by partial transection of the infraorbital nerve (pT-ION) in mice." (PMID 36187288, 2022). "In this study, using an OVX rat model, we tested whether estrogen exerts anti-anxiety effects by impacting the LHb and explored the underlying mechanisms involved." (PMID 35615566, 2022). "Anxiety-like behavior in postpartum mice, which is generated by removal of their pups, has been shown to be associated with increased Fos-immunoreactive cell counts in the LHb, suggesting an association between LHb activation and maternal anxiety-like behavior." (PMID 35615566, 2022). "Thus, the impairment in memory persistence caused by LHb inactivation cannot be attributed to general effects over animals' motility or anxiety state." (PMID 24860453, 2014). "Moreover, the inhibitory inputs from the LHb have been proved to involve in manipulating reward-related activities, and this function has been linked to 5-HT modulation and DA transmission, which can produce anxiety-like behaviors." (PMID 35145415, 2022). "Early research suggests that modulating LHb functionality by altering glutamate or GABA transmission can induce anxiety-like behaviors." (PMID 40635883, 2025). "This discovery presents a novel pharmacological approach for targeting the yohimbine mechanism in developing new anxiety treatments focused on the LHb." (PMID 40635883, 2025). "In the neurobiological context of anxiety, the LHb interacts with diverse neurotransmitters, modulating anxiety-related behaviors." (PMID 40635883, 2025). "We then evaluated the effects of LHb neuron-specific knockdown of TCF7L2 on anxiety, learning, memory, and social behavior." (PMID 39596468, 2024). "Next, we evaluated the effects of LHb neuron-specific overexpression of TCF7L2 on anxiety, learning, memory, and social behavior." (PMID 39596468, 2024). "Meanwhile, although NK3R was significantly decreased after pT-ION, we found that the exogenous agonist senktide induced robust suppression of both LHb neuronal firing and allodynia/anxiety behaviors." (PMID 36756128, 2023). "In previous work and the present work, we reported that overexpression of NK3R rescued the pT-ION-induced allodynia/anxiety behaviors and the increase in the synaptic activity of LHb neurons, which showed the action of the endogenous NKB ligand." (PMID 36756128, 2023). "This is in accordance with the fact that LHb dysfunction induces anxiety-like behaviors on the elevated plus maze." (PMID 35308564, 2022). "Our findings indicated that the NR2B/CaMKII pathway of the LHb contributed to the occurrence and development of orofacial pain and anxiety-like behaviors in pT-ION model mice." (PMID 36187288, 2022). "Our previous study demonstrated that the LHb regulates pain and anxiety-like behaviors in a mouse model of TN." (PMID 36187288, 2022). "Our previous study demonstrated that the LHb is involved in the occurrence and development of pain and the related anxiety induced by TN." (PMID 36187288, 2022). "Based on this research, we further investigated the mechanisms by which the LHb contributes to pain and anxiety in cases of trigeminal nerve injury." (PMID 36187288, 2022).
Anxiety (continued). "We showed that pT-ION-induced hyperexcitability of LHb neurons and chemicogenetic inhibition of LHb neuronal activity alleviated the pT-ION-induced anxiety-like behaviors." (PMID 32264959, 2020). "In our study, we found that pAMPK levels in anxiety-related brain regions like LHb, hippocampus, and basal ganglia were increased compared with the HFD group." (PMID 31681174, 2019). "In a separate cohort, we sought to determine the role of the LHb in IS-induced anxiety-like behavior measured during subsequent JSI." (PMID 27785462, 2016). "Here, optogenetic silencing of the LHb during IS blocked the typical anxiety-like behaviors produced by IS in male rats." (PMID 27785462, 2016). "Optogenetic silencing of the LHb restricted to the tailshock intervals of an IS session blocked the typical increase in anxiety-like behavior observed 24 h later in the JSI test." (PMID 27785462, 2016). "Successively, we confirm that the LHb lesion induces hyperactivity and we show, for the first time, it reduces anxiety state and emotionality." (PMID 26082682, 2015). "Our current findings support and extend these prior studies by showing that the inactivation of the LHb per se decreases anxiety-like traits in rats (i.e., increase in head-dipping), an effect never observed before." (PMID 26082682, 2015). "Such evidence is suggestive of the important role of the LHb in the behavioral organization of the animal following pharmacological modulation (i.e., nicotine) of its emotional reactivity (i.e., anxiety) and in behavioral response to stress." (PMID 26082682, 2015). "To control for general effects of LHb blocking over motility or anxiety we analyzed the effect of the infusion of muscimol into the LHb 30 min before subjecting animals to an open field and an elevated plus maze tests." (PMID 24860453, 2014). "Our results extend recent findings that pharmacological inactivation of the LHb blocks yohimbine-induced potentiation of cue-dependent reinstatement of cocaine-seeking, as well as attenuating yohimbine-induced anxiety-related behaviors." (PMID 24695107, 2014). "The LHb plays a pivotal role in the pathophysiology of stress-related anxiety conditions." (PMID 40635883, 2025). "Additionally, we found that globally inhibiting LHb neurons also significantly reduced AS‐induced anhedonia, despair‐like, and anxiety‐like behaviors, as well as the AS‐induced increase in bursting and hyperpolarization of the RMP in LHb neurons." (PMID 38863324, 2024). "In contrast, pharmacological inhibition of NK3R in the LHb induced anxiety-like behaviors in naive mice by activating neurons in the LHb, which indicated that enhanced LHb activity could lead to depressive-like or anxiety-like effects in healthy naive rodents." (PMID 36756128, 2023). "However, in the OFT the central time, central distance, and central/total distance were reduced by CNO administration, indicating that activation of bilateral LHb glutamatergic neurons in naive mice induced anxiety-like behaviors in the OFT." (PMID 36756128, 2023). "In addition, the LHb is associated with multiple psychiatric morbidities, and the activation of the LHb has been shown to mediate anxiety-like behavior in patients with temporomandibular disorder." (PMID 36756128, 2023). "As we show in this study, chemogenetic inhibition of the release of NKB in the fPAG reversed the alleviating effect of Tacr3 overexpression on pT-ION-induced allodynia and anxiety-like behaviors, indicating that fPAGNKB → LHb regulates orofacial allodynia and anxiety-like behaviors in pT-ION mice." (PMID 36756128, 2023). "Indeed, it has been shown that the LHb participates in behavioral responses such as pain, anxiety, reward and stress." (PMID 37445871, 2023). "Considering that the CeA and LHb are crucial for anxiety, the DRN5-HT+-CeASOM+-LHb circuit might also be important for the comorbidity of pain and anxiety." (PMID 35211169, 2022).